MTOR (mechanistic target of rapamycin kinase)
Diseases named in the same sentence as MTOR in open-access papers (continued):
Sharing a sentence is not in itself a finding about the gene and the disease.
hepatocellular carcinoma (continued). "Chlorogenic acid is reported to enhance the sensitivity of human hepatocellular carcinoma cells lines to regorafenib treatment by inhibiting PI3K/Akt/mTOR signaling and lessening liver injury by inhibiting autophagy in a rat model of NAFLD." (PMID 34684653, 2021). "For example, the lncRNA MALAT1, which owned the largest subnetwork and largest loss proportion, was found to regulate cancer glucose metabolism by enhancing mTOR-mediated translation of TCF7L2 in hepatocellular carcinoma." (PMID 34222227, 2021). "In conclusion, ropivacaine suppressed tumor biological characteristics and promoted apoptosis, resulting in the suppression of hepatocellular carcinoma progression by targeting the IGF-1 R/PI3K/AKT/mTOR signaling pathway." (PMID 34696683, 2021). "The most significant pathways included hepatocellular carcinoma, proteoglycans in cancer, and the mammalian target of rapamycin (mTOR) signaling pathway." (PMID 33574968, 2021). "We found that the phosphorylation of both mTOR and S6rp, an mTOR downstream effector, was decreased in peritoneal macrophages exposed to the conditioned medium of hepatoma cells." (PMID 34552122, 2021). "Baicalin induced ROS-dependent autophagy in oral squamous cell carcinoma and induced autophagy by activating ER stress, inhibiting the AKT/mTOR pathway in hepatocellular carcinoma." (PMID 33494431, 2021). "Anlotinib can inhibit the phosphorylation of Akt and mTOR in several types of cancer like hepatocellular carcinoma, colon cancer and intrahepatic cholangiocarcinoma, supporting the phosphoproteomics analysis in this work." (PMID 33748143, 2021). "STGPT repressed N-nitrosodiethylamine-induced murine hepatocellular carcinoma progression by inhibiting HIF-1α via the interference with the AKT-AMPKα-mTOR axis and the interruption of IKKβ, P38α, and ERK1/2 signals as well." (PMID 35095479, 2021). "Our recent study demonstrated that HBV inhibited lysosomal activity is restored to enhance HBV antigens degradation by inhibiting Akt/mTOR signaling after silencing CCDC88A in hepatoma cells with HBV replication." (PMID 34580816, 2021). "EGCG upregulates AMPK activity in a dose-dependent manner, while the mTOR pathway is inhibited in hepatoma cells." (PMID 34575981, 2021). "BT is also reported to induce autophagy and apoptosis in hepatocellular carcinoma via inhibition of the PI3K/AKT/mTOR pathway." (PMID 34221237, 2021). "MiR-132 also inhibits proliferation in hepatocellular carcinoma (HCC) by inactivating the AKT / mTOR signaling pathway, and by inhibiting IL1β and IL6 expression through inhibition of the transcriptional co-activator P300." (PMID 33539381, 2021). "Tumor cell-intrinsic PD-1 promotes tumor occurrence such as hepatocellular carcinoma and melanoma by activating the mTOR signaling." (PMID 34539884, 2021). "Although no report has suggested raptor or rictor as prognostic markers in head and neck cancer, in hepatocellular carcinoma, high levels of mTOR and rictor mRNA are an indicator of early recurrence after hepatic resection." (PMID 33482765, 2021). "A recent study has shown that activation of PI3K/AKT/mTOR signaling increases hepatocellular carcinoma resistance to radiotherapy." (PMID 34335799, 2021). "Combined with previous studies, we assumed that the local anesthetic ropivacaine potentially participated in hepatocellular carcinoma progression by regulating the IGF-1 R-PI3K-Akt-mTOR signaling pathway." (PMID 34696683, 2021). "Another pathway, phosphatase and tensin homolog (PTEN)/mTOR/nuclear factor kappa B (NF-κB), is also mediated by OA in the process of hepatoma proliferation and progression." (PMID 34434893, 2021). "The use of mTOR inhibitors, which were selectively used in recipients with advanced stages of hepatocellular carcinoma, independently increased the development of significant hypercholesterolemia." (PMID 33441656, 2021).
hepatocellular carcinoma (continued). "To investigate the mechanism of how SSd increases radiosensitivity by inducing autophagy in hepatoma cells, we detected changes of mTOR expression and its downstream proteins by Western blot." (PMID 33628104, 2021). "For example, the mTOR pathway is able to participate in the malignant progression of hepatocellular carcinomas by activating SNRPA1." (PMID 34283076, 2021). "Consistent with the previous research results, our data suggested that myristicin suppresses the activation of the PI3K/Akt/mTOR signalling pathway in hepatic carcinoma." (PMID 34410900, 2021). "Here, we explored the effect of defined genetic changes on the transcriptome, proteome and phosphoproteome in twelve tumors from an mTOR-driven hepatocellular carcinoma mouse model." (PMID 34348664, 2021). "Myristicin prevents the malignant biological behaviour of hepatic carcinoma cells by inhibiting the PI3K/Akt/mTOR signalling pathway." (PMID 34410900, 2021). "miR-149 inhibits the tumorigenesis of hepatocellular carcinoma (HCC) via directly targeting AKT1 to regulate the AKT/mTOR pathway." (PMID 34869377, 2021). "Research based on rapalogs, among others with everolimus, have shown that observation of phosphorylation of mTOR (Ser2481) allowed for the correct prediction of the therapeutic efficacy of mTORC1 inhibitors against hepatocellular carcinoma." (PMID 31586300, 2020). "This lncRNA enhances the ubiquitin-mediated destruction of PKM2 and suppresses Akt/mTOR signaling pathway to stop aerobic glycolysis in hepatocellular cancer cells." (PMID 33123468, 2020). "mTOR is a validated target of miR-199a-3p and miR-100 miRNAs in hepatocellular carcinoma and ovarian cancer, respectively." (PMID 32326380, 2020). "Meanwhile, SC66 induced changes in cytoskeletal organization and ROS production, resulting in phosphorylated AKT level was notably decreased, and demonstrated that SC66 remarkably inhibit tumor growth via AKT/mTOR/β-catenin pathway in hepatocellular carcinoma." (PMID 32848734, 2020). "More recently, overexpression of BZW2 has been identified to be associated with hepatoma cell drug resistance, and inhibition of BZW2 inhibits cell proliferation, migration, and invasion by regulating PI3K/Akt/mTOR signaling pathway." (PMID 33005104, 2020). "Overexpression of miR-21 in hepatoma cell line had shown increased phosphorylation p70S6K, the downstream regulator of cell proliferation in mTOR pathway." (PMID 33614488, 2020). "In hepatocellular carcinoma cells, miR‐223 is found to target Rab1, which is critical for mTOR pathway, and to promote apoptosis." (PMID 32491253, 2020). "In detail, hispidulin induced ER stress-mediated apoptosis in hepatocellular carcinoma cells by activating the 5′ AMP-activated protein kinase (AMPK)/mammalian target of rapamycin (mTOR) pathway." (PMID 32168739, 2020). "Further, CAF inhibit apoptosis of Huh7 hepatoma cells via SDF-1/CXCR4/PI3K/AKT/mTOR signaling and further promote proliferation of the malignant hepatocytes." (PMID 32899119, 2020). "A previous study reported that miR-7 functioned as a tumor suppressor and played an important role in inhibiting tumorigenesis and reversing the metastasis of hepatocellular carcinoma (HCC) through the PI3K/Akt/mTOR-signaling pathway in vitro and in vivo." (PMID 32089682, 2020). "Brusatol activates autophagy of hepatoma cells by inhibiting PI3K/AKT/mTOR pathway, thereby effectively inducing apoptosis of hepatoma cells, inhibiting proliferation of hepatoma cells as well as invasion and migration of tumors." (PMID 31835352, 2019). "mTOR inhibitors have been thoroughly tested as immunosuppressant agents and are specially recommended in patients with liver transplantation for hepatocellular carcinoma." (PMID 31450639, 2019). "Molecular studies have identified that the majority of hepatocellular carcinomas show aberrantly activated PI3K/AKT/mTOR and Wnt/β-catenin signaling pathways." (PMID 30678274, 2019).
hepatocellular carcinoma (continued). "Here, it found that the novel functions of miR-29 on the phosphorylation of AKT/mTOR indicating control hepatocellular carcinoma cell proliferation via the overexpression of miR-29a." (PMID 30917489, 2019). "The mTOR pathway is responsible for the involvement of 30–40% of hepatocellular carcinoma (HCC) cases." (PMID 31557936, 2019). "SAHA or OSU-HDAC42 also induced autophagy and autophagy-mediated cell death in hepatocellular carcinoma cells by repressing the AKT/mTOR signaling pathway." (PMID 31861179, 2019). "Previous studies demonstrated ATG7 and mTOR as the target genes of miR-199a-5p involved in the regulation of the autophagic process in hepatocellular carcinoma and hypertrophic hearts." (PMID 31636666, 2019). "Previous studies have reported an oncogenic function of Rab1A in colorectal cancer and hepatocellular carcinomas via the mTOR pathway." (PMID 31527621, 2019). "More recent reports indicate that IL-37 induces autophagy in hepatocellular carcinoma by inhibiting the PI3K/AKT/mTOR pathway and suppresses tumor activity in renal cell and small lung cell carcinoma." (PMID 31781119, 2019). "Melatonin-induced autophagy via the PI3K/Akt/mTOR pathway has been observed in a number of different cancer cells, such as hepatoma cells." (PMID 31870319, 2019). "In liver cancer, inhibition of mTOR-mediated hepatoma cell protective autophagy can accelerate the death of liver cancer cells, and thus alleviate the malignant development of liver cancer." (PMID 31835352, 2019). "On the contrary, IL-17A inhibited autophagy via TAB2/TAB3-p38 mitogen-activated protein kinase pathways and mTOR signaling in Hepatocellular carcinoma (HCC) cells and keratinocytes." (PMID 31921197, 2019). "Studies have revealed that mTOR/AKT pathways are frequently up-regulated in 40–50% of hepatocellular carcinoma's." (PMID 31293977, 2019). "For instance, as a novel anticancer drug, the main mechanism by which Britannin (Bri) inhibits the growth and proliferation of hepatoma cells is to over-activate AMPK/mTOR pathway-mediated autophagy to promote autophagic cell death." (PMID 31835352, 2019). "For example, miR-96 and miR-199a-3p target mTOR in prostate cancer cells and hepatocellular carcinoma, respectively." (PMID 30518907, 2019). "Blocking mTOR signaling strongly sensitizes cells to inhibition by ponatinib and makes ponatinib a much more potent inhibitor of hepatocellular carcinoma cell proliferation." (PMID 30959969, 2019). "The overexpression of the PI3K-Akt-mTOR pathway can promote the migration and proliferation as well as inhibiting the apoptosis of hepatoma cells, which is related to highly reduced survival." (PMID 31015849, 2019). "Recent study had reported that H2S promotes autophagy via the PI3K/Akt/mTOR signaling pathway in hepatocellular carcinoma cells." (PMID 30210332, 2018). "This study aims to evaluate the effect of Celastrus orbiculatus extract (COE) on the apoptosis in human hepatic carcinoma HepG2 cells with mTOR overexpression." (PMID 30526568, 2018). "JNU-144 treatment inhibits hepatoma cells growth and proliferation by downregulating mTOR activation." (PMID 30177727, 2018). "The natural compound bafilomycin A1 activates early stage of autophagy by downregulating mTOR pathway, and inhibits later stages of autophagy in hepatocellular carcinoma involving PUMA43." (PMID 30584259, 2018). "Further, synergy between DXR and targeted mTOR inhibition has been reported in hepatocellular carcinoma in vivo models." (PMID 30046395, 2018). "Previously, we demonstrated that BDE-47 activates mTOR (mechanistic target of rapamycin) signaling in mouse livers and in human hepatocellular carcinoma cells." (PMID 30294300, 2018).
hepatocellular carcinoma (continued). "Our studies revealed that JNU-144 suppressed cell viability and proliferation in hepatoma cells by downregulating mTOR activation." (PMID 30177727, 2018). "Human hepatic carcinoma HepG2/mTOR+ cells were treated with different concentrations (20, 40, 80, 160, and 320 μg/mL) of COE for 24 h." (PMID 30526568, 2018). "The mTOR pathway is a major tumor-initiating pathway in hepatocellular carcinoma, with up-regulation seen in up to 50% of tumors." (PMID 29385181, 2018). "In a similar protocol, simultaneous application of the mTOR inhibitor sirolimus and vorinostat led to stable disease in hepatocellular carcinoma patients." (PMID 29299126, 2017). "There is lots of evidence to support the critical involvement of mTOR signaling in the carcinogenesis of hepatocellular carcinoma (HCC)." (PMID 27935857, 2017). "Arenobufagin has been found to suppress adhesion, migration, and invasion and to induce apoptosis and autophagy via inhibition of the phosphatidylinositol 3-kinase (PI3K)/AKT/mammalian target of rapamycin (mTOR) pathway in human hepatoma cell lines." (PMID 29137423, 2017). "LINC00152 is also involved in hepatocellular carcinoma oncogenesis via activation of the mechanistic target of rapamycin (mTOR) signaling pathway." (PMID 28719640, 2017). "De-regulation of the mTOR pathway is frequently found in human cancers, including hepatocellular carcinoma (HCC), the most common form of primary liver cancer." (PMID 29088718, 2017). "Persistent activation of IGF1R/mTOR signaling pathway plays crucial role in the development of hepatocellular carcinoma (HCC)." (PMID 28624790, 2017). "Significantly increased FFA levels have been reported in hepatic carcinoma patients, with effects dependent upon the mTOR/NF-κB pathway." (PMID 27816967, 2016). "MiR-7 was reported to function as a tumor suppressor and plays a substantial role in inhibiting the tumorigenesis and reversing the metastasis of hepatocellular carcinoma through the PI3K/AKT/mTOR-signaling pathway both in vitro and in vivo." (PMID 26701847, 2016). "Kinase signaling pathway such as PI3K/AKT/mTOR has been reported to be involved in the PPI-activated autophagy in human hepatocellular carcinoma (HCC) cells." (PMID 27421653, 2016). "Bufalin has been shown to induce cell cycle arrest and autophagy in human hepatoma cells in response to AKT/mTOR pathway activation." (PMID 27518192, 2016). "microRNA-100 promotes the autophagy of hepatocellular carcinoma cells by inhibiting the expression of mTOR and IGF-1R." (PMID 25877859, 2015). "Hepatitis B virus (HBV) pre-S2 mutant can induce hepatocellular carcinoma (HCC) via the induction of endoplasmic reticulum stress to activate mammalian target of rapamycin (MTOR) signaling." (PMID 25909713, 2015). "The key signal transduction pathways that have been implicated in the pathogenesis of hepatocellular carcinoma are the EGFR, Ras/Raf/Mek/Erk, phosphoinositide 3-kinase/Akt, mTOR, HGF/c-Met, Wnt, and Hedgehog signaling cascades." (PMID 25895026, 2015). "Inhibition of mTOR phosphorylation by rapamycin enhanced the radiosensitivity of BKM120-treated hepatocellular carcinoma cells." (PMID 25004403, 2014). "mTOR (a downstream effector of Akt) is also highly activated in aggressive HCC, and mTOR activation plays an important role in hepatoma cell growth and development." (PMID 24721996, 2014). "BCAA supplementation decreases the incidence of hepatocellular carcinoma, the mTOR signalling pathway deeply contributes to tumor formation, and cellular senescence is one of the tumor suppression mechanisms." (PMID 24223226, 2013). "Our study was designed to determine autophagic flux in matrine-treated hepatoma cells and revealed the association of matrine-induced autophagy with PI3K/AKT/mTOR pathway and beclin-1." (PMID 24287900, 2013).
hepatocellular carcinoma (continued). "It has been shown that amino acids regulate protein synthesis through mTOR, and that leucine activates mTOR in the hepatic carcinoma cell lines." (PMID 24223226, 2013). "Furthermore, mTOR-inhibitor-based immunosuppression is associated with survival benefits for patients with hepatocellular carcinoma (HCC) who have received liver transplantation." (PMID 24403259, 2013). "Aberrant mTOR signaling has been detected in up to 48% of hepatocellular carcinoma, and a correlation between poor outcome and mTOR signaling activation has been shown." (PMID 23167739, 2012). "In order to draw a light on genetic alterations of PI3K/AKT/mTOR signaling in hepatocellular carcinoma, DNA sequencing of human tumor samples were performed." (PMID 23167739, 2012). "5′AMP-activated protein kinase (AMPK) and the mammalian target of rapamycin (mTOR) are two serine/threonine protein kinases and potential targets for cancer chemotherapy against hepatocellular carcinoma cells." (PMID 22582152, 2012). "The mTOR pathway, important in energy metabolism and protein translation, is activated in 47% of FLCs, a finding similar to typical hepatocellular carcinoma." (PMID 24278737, 2012). "The PI3K/AKT/mTOR signaling pathway is a promising target with respect to its frequent dysregulation in hepatocellular carcinoma and its central role in regulating cell proliferation, migration, survival and angiogenesis." (PMID 23167739, 2012). "Hepatoma cells are also a relevant model because resveratrol has been proposed as a chemopreventative agent for human hepatocellular carcinoma a disease in which the mTOR pathway is often constitutively activated." (PMID 22242130, 2011). "Mammalian target of rapamycin (mTOR) inhibitors, including sirolimus (rapamycin) and temsirolimus, are potential therapeutic agents for hepatocellular cancer and renal cell carcinoma due to their anti-proliferative and anti-angiogenic properties." (PMID 20298531, 2010). "The mTOR inhibitor rapamycin has anti-tumor activity across a variety of human cancers, including hepatocellular carcinoma." (PMID 19816606, 2009). "Chemotherapeutic agent, 5-Fu, down-regulated telomerase activity at both transcriptional level and PI3K/Akt/mTOR pathway-dependent post-transcriptional level to facilitate hepatocellular carcinoma cell apoptosis." (PMID 17996122, 2007). "Likewise, a prior study focusing on hepatocellular carcinoma revealed that activating the AKT/mTOR pathway was able to raise SREBP‐1 expression levels, thereby restructuring hepatic lipid metabolism." (PMID 40928061, 2026). "Research has demonstrated that the PI3K / AKT / mTOR route is one of the principal signaling pathways that regulate glucose metabolism in cancer cells and it is involved in metabolism in some malignant tumors such as hepatocellular carcinoma and so on." (PMID 39869954, 2025). "The previous studies demonstrated that OA induced autophagy in colon cancer cells by regulating the p38/FOXO3a/Sirt6 pathway, and in hepatoma cells through the Akt/mTOR pathway, reflected in the decreased p62 expression and increased LC3-II and Beclin-1 expression." (PMID 40969279, 2025). "Among which, the Ras signaling pathway, Hepatocellular carcinoma, Proteoglycans in cancer, Gastric cancer, NF-kappa B signaling pathway, mTOR signaling pathway, Hippo signaling pathway and Wnt signaling pathway were widely reported to correlate with various cancers." (PMID 40070576, 2025). "This could be possibly attributed to the limited understanding of the intricate interactions and metabolic roles of the PI3K/Akt/mTOR signaling axis in hepatoma." (PMID 40179068, 2025). "Similarly, isoquercitrin has been shown to induce both apoptosis and autophagy in hepatocellular carcinoma cells by modulating the AMPK/mTOR/p70S6K signaling axis, further supporting its role as an AMPK activator." (PMID 40141359, 2025).